BTBD6 (BTB domain containing 6)
Description:
Adapter protein for the cul3 E3 ubiquitin-protein ligase complex (By similarity). Involved in late neuronal development and muscle formation (By similarity).
Synonyms: BDPL
Tractability: Antibody: UniProt predicts a signal peptide or a membrane-spanning region. PROTAC: ubiquitination databases record sites on it.
Gene: Protein-coding gene on chromosome 14 (105,248,533 to 105,251,110, forward strand). Ensembl gene ENSG00000184887.
Subcellular location: Cytoplasm
Subcellular location (Human Protein Atlas): Nucleoplasm
Pathways (Reactome):
Immune System: Antigen processing: Ubiquitination & Proteasome degradation
Metabolism of proteins: Neddylation
Gene Ontology:
Biological process: neurogenesis
Cellular component: cytoplasm; cytosol
Genetic constraint (gnomAD): Loss-of-function variants: 30 observed, 38.48 expected, observed/expected ratio (o/e) 0.78, 90% interval 0.58 to 1.06. The synonymous counts are far from expectation, so gnomAD's model fits this gene poorly and the ratio says little. Missense variants: 698 observed, 658.03 expected, observed/expected ratio (o/e) 1.06, 90% interval 1 to 1.13. Synonymous variants: 378 observed, 295.38 expected, observed/expected ratio (o/e) 1.28, 90% interval 1.18 to 1.39.
Homologues: Orthologues: mouse Btbd6 (91% identical), rat Btbd6 (90% identical), chimpanzee BTBD6 (90% identical), pig BTBD6 (90% identical), macaque BTBD6 (90% identical), guinea pig BTBD6 (88% identical), tropical clawed frog btbd6 (81% identical), dog BTBD6 (80% identical), zebrafish btbd6b (73% identical), rabbit BTBD6 (72% identical), Drosophila melanogaster lute (58% identical), Drosophila melanogaster CG17068 (25% identical), and 2 more. Paralogues in human: BTBD3 (66% identical), BTBD2 (41% identical), BTBD1 (38% identical), BTBD9 (21% identical), ABTB2 (20% identical), ABTB3 (19% identical), KBTBD4 (18% identical), ABTB1 (14% identical), SPOPL (12% identical), SPOP (11% identical), KLHL11 (9% identical).
Diseases named in the same sentence as BTBD6 in open-access papers:
BTBD6 is named in the same sentence as 3 diseases in open-access papers, as found by Europe PMC text mining. Sharing a sentence is not in itself a finding about the gene and the disease. The quoted sentences say what the papers report.
uveal melanoma (2 papers, 2025 to 2026). A melanoma derived from melanocytes of the uveal tract. "In the uveal melanoma cohort, a six‐molecule signature (ARPC1B, BTBD6, GUSB, KRTCAP2, RHBDD3, and SLC39A4), which was associated with glycolysis and the immune response, was established and used for survival prediction and risk stratification of these patients." (PMID 39830021, 2025).
tumor (3 papers, 2019 to 2022). "The top genes in cold tumor are ARF1, PDIA3, ALDOA, FKBP2, NDUFS5, NDUFC1, COX7A2, C14orf2, LNX1, and BTBD6." (PMID 33816503, 2021). "The expression levels of five genes (ADAM28, BTBD6, CXCL5, PCDH1, and LOC102724689) comprise three rules for the identification of pancreatic-tissue-derived PDX tumor tissues." (PMID 31456818, 2019).
BTBD6 also shares sentences with these, for which no sentence is quoted: lung carcinoma (1 paper).